WNT2 (Wnt family member 2)
Diseases named in the same sentence as WNT2 in open-access papers (continued):
Sharing a sentence is not in itself a finding about the gene and the disease.
tumor (continued). "This demonstrates Wnt2-positive CTCs are present at subclonal level and represent a rare subset of the primary tumor population." (PMID 26980749, 2016). "There was a significant associstion between high WNT2 expression and tumor size, LVSI, positive parametrium." (PMID 27513465, 2016). "In metastatic pancreatic cancer, RNA-ish was used for detection of CTC-specific transcripts of Wnt2, which is known for its role in tumor sphere formation and metastasis initiation." (PMID 26980749, 2016). "This phenomenon consists with the results in a previous report that in tumour cells, Wnt2 was one of the genes with over 2-fold down-regulation by HMGA2." (PMID 25300915, 2015). "We selected 5 CpG loci with significant methylation differences by tumor histology (q-value < 2.2E-16 and fold-change > 2.50) for validation by Pyrosequencing (HOXA9_E252_R, SOX1_P294_F, WT1_E32_F, WNT2_P217_F, MDR1_seq_42_S300_R)." (PMID 23806198, 2013). "To identify whether Wnt-2 is produced in close proximity to the invasive border of tumor cells, we performed RNA in situ hybridization, probing for WNT2 and FAP within ATC tumors." (PMID 39951495, 2025). "Additionally, pan-cancer analysis highlighted the tissue- and tumor-specific expression patterns of WNT2, WNT7B, and WNT11 across various cancers, in agreement with previous studies." (PMID 41044153, 2025). "The Wnt2/β-catenin pathway, activated in many types of cancers and playing a significant role in its progression, is also inhibited in response to SAMe treatment in retinoblastoma showing tumor growth reduction in a xenograft animal model." (PMID 39941901, 2025). "Wnt2, a canonical Wnt ligand, is implicated in esophageal squamous-cell carcinoma (ESCC) carcinogenesis, being absent in normal esophageal epithelium but present in over 50% of ESCC cases, with expression increasing with tumor grade." (PMID 40943055, 2025). "In NPC, ALKBH5 cooperated with YTHDF1 to stabilize WNT2 mRNA and elevate WNT2 protein levels, which not only promoted M2 polarization of TAMs but also enhanced tumor cell proliferation and metastasis via autocrine activation of the FZD2/β-catenin axis, establishing a vicious cycle." (PMID 41562066, 2025). "The angiogenic capacity of tumor vessels is significantly reduced when WNT2 is silenced in CAFs." (PMID 40677714, 2025). "Anti-WNT2 monoclonal antibodies not only restore DC differentiation but also enhance T cell activation, improving the anti-tumor immune response and boosting the efficacy of immune checkpoint inhibitors in tumor models." (PMID 40453074, 2025). "Recently, it was found that using WNT2 monoclonal antibody with PD-1 monoclonal antibody significantly restored intra-tumor anti-tumor T cell responses and improved anti-PD-1 efficacy in mouse OSCC and CRC homologous tumor models by increasing the number of active DCs." (PMID 37007004, 2023). "In addition, in mice ESCC and colorectal cancer homologous tumor models, the anti-WNT2 monoclonal antibody greatly restored anti-tumour T-cell responses and enhanced the therapeutic effect of anti-PD-1 treatment." (PMID 37927475, 2023). "WNT2 has a pivotal role in sustaining an activated CAF phenotype, which is associated with the maintenance of a pro-angiogenic secretome and contributes to elevated tumor angiogenesis in CRC." (PMID 35936516, 2022). "Moreover, circLMO7 can also promote the glutamine metabolism of GC cells through the WNT2/β-Catenin pathway to provide energy for tumor growth." (PMID 33397440, 2021). "Moreover, Wnt2 expression is positively correlated with the invasion potential, tumor stage, and clinical grade of malignant tumors." (PMID 34375306, 2021). "Based on these discoveries, it is tempting to speculate that the transcriptional reprogramming initiated by CAF-secreted IL-6 or Wnt2 could shift the balance toward proangiogenic signals in favor of tumor angiogenesis and proliferation." (PMID 34660589, 2021).
tumor (continued). "Among other tumor cell lines, WNT2 and ZNF726 had the highest methylation in CRC, indicating that the role of WNT2 and ZNF726 genes in the CRC may be linked to methylation regulation." (PMID 34217303, 2021). "Moreover, WNT2 knockdown in EC9706 tumors significantly suppressed tumor growth and tumor burden (Student’s t-test, p value < 0.05)." (PMID 32699215, 2020). "Although high expression of WNT2 is not a prognostic marker, it was associated with tumor progression." (PMID 32699215, 2020). "TCGA-ESCC cohort suggested higher expression of WNT2 is a biomarker of tumor progression." (PMID 32699215, 2020). "In this study, we use human umbilical vein endothelial cells (HUVECs) as well-established model system for angiogenic processes in combination with a novel angiogenesis assay, which allows to address the impact of WNT2 expression in colon CAFs on tumor vessel development." (PMID 31667643, 2020). "Furthermore, we concluded that if WNT2 is critically involved in tumor angiogenesis in humans, the outcome for overall survival would be influenced by WNT2 levels similarly to PECAM1 levels, directly indicating the amount of vascularization in the tumors." (PMID 31667643, 2020). "In CRC xenografts, WNT2 overexpression resulted in enhanced vessel density and tumor volume." (PMID 31667643, 2020). "Cancer-associated fibroblasts were identified as the main source of Wnt2, and Wnt2 could enhance the tumor growth and the invasion of CRC in a paracrine fashion." (PMID 32923386, 2020). "Wnt2 overexpression promotes tumor growth, migration, invasion, and metastasis." (PMID 32983993, 2020). "Increased WNT2 expression is detectable in many carcinomas and participates in tumor progression." (PMID 31667643, 2020). "Thus, in vitro experiments were conducted to explore how Wnt2 induced tumor progression through the interaction between cancer cells and CAFs in CRC." (PMID 31468733, 2019). "Furthermore, we identified a cytokine basket that pinpoints the relationship between WNT2 overexpression and an immune-permissive tumor-environment." (PMID 31277479, 2019). "Interestingly, in breast cancer bone metastases, the Wnt/β-catenin signaling pathway seems to be active inside the tumor with overexpression of canonical Wnt ligands (Wnt2 and Wnt8b), maintaining tumor cell proliferation." (PMID 31370265, 2019). "Conversely, Wnt2 and Wnt8b are downregulated at the tumor/bone interface while Wnt antagonists WIF1 and SFRP4 are overexpressed and could be responsible, at least in part, of suppression of osteoblast proliferation and enhanced bone destruction by osteoclasts." (PMID 31370265, 2019). "The expression of Wnt2 and Fzd9 was also correlated with the tumor stages." (PMID 28665975, 2017). "The majority of Wnt2-positive cells were located around tumor nest." (PMID 26822225, 2016). "For example, WNT2 is up-regulated in gastric cancers, and could impact tumor formation, invasion and dissemination." (PMID 27513465, 2016). "It was revealed that Wnt2 secreted by CAFs was able to mediate tumor cell growth." (PMID 26822225, 2016). "Moreover, enrichment of the Wnt-2 gene in circulating tumor cells was identified using RNA sequencing." (PMID 23815780, 2013). "In GC, overexpression of Wnt ligands (Wnt2, Wnt3, and Wnt5A) and receptors (FZD7 and LRP5/6) is associated with more advanced disease, poorer prognosis, and elevated metastatic potential, while β-catenin and reduced APC expression further underline more aggressive tumor behavior." (PMID 40943055, 2025).
tumor (continued). "Furthermore, QZACP induced irreversible cell cycle arrest in stressed tumor cells by up-regulating the expression of p21 and promoting the secretion of PASP factors (decorin, CXCL14, and Wnt family member 2) within tumor cells after recruiting NK and CD8+ T cells." (PMID 39206194, 2024). "The results indicate that WNT2/2B/11 may be able to predict the tumor progression of LUAD patients." (PMID 35957916, 2022). "Therefore, we hypothesized that WNT2 might be related to the circLMO7-miR-30a-3p axis and play a promoting role in tumor development." (PMID 33397440, 2021). "In addition, upregulated expression of WNT2 in tumor fibroblast cells, which was observed in this study, could also result in tumor growth and promotion of invasion by activating the canonical WNT/β-catenin signaling pathway." (PMID 34900703, 2021). "Importantly, when the WNT2/LRP5/LRP6 canonical Wnt signature was used for analysis using STAD tumor data, the modest correlation with TAMs (compare lines 2b, 6b) and M2 markers (compare lines 4b, 8b) was lost, favoring a role for the non-canonical Wnt pathway in macrophage infiltration." (PMID 33869179, 2021). "However, there is scarce evidence about WNT2 function in tumor angiogenesis." (PMID 31667643, 2020). "As WNT2 RNA expression in ESCC cell lines is significantly higher than in normal cell lines, we tested whether WNT2-mediated signaling was required for tumor cell growth, we suppressed WNT2 expression using two independent short interfering (si)RNAs in two ESCC cell lines (EC9706 and EC109)." (PMID 32699215, 2020). "Furthermore, WNT2, which is also known to be a robust factor that mediates tumor-stromal interactions, is one of the up-regulated WNT genes in cancer-associated fibroblasts isolated from primary ESCC, which may contribute to the invasiveness of ESCC cells." (PMID 32766155, 2020). "However, positive staining for Wnt2 was equally observed in right and left side tumor." (PMID 31468733, 2019). "Therapeutic interventions using an anti-WNT2 monoclonal antibody have been shown to increase antigen-presenting DCs within tumors, correlating with enhanced CD8+ T cell responses and tumor suppression." (PMID 40453074, 2025). "Specifically, miR‐146a‐5p has been reported to bind directly to WNT2, EGFR, NOTCH2, TRAF6, IRAK1 and EIF5A2 to inhibit EMT and act as a tumour suppressor in various human cancers." (PMID 40785027, 2025). "EC is characterized by elevated expression of multiple Wnt ligands (notably Wnt2, Wnt3, Wnt5A, and Wnt6) and FZD receptors, often correlating with poorer differentiation, higher potential of tumor invasion, and shorter survival." (PMID 40943055, 2025). "Elevated expression of Wingless-type MMTV integration site family member 2 (WNT2) has been observed in CRC, facilitating tumor cell invasion and dissemination." (PMID 41409281, 2025). "Specifically, CAF-derived WNT2 disrupts the JAK2/STAT3 signaling pathway, essential for maintaining DC differentiation, leading to diminished anti-tumor immunity." (PMID 40453074, 2025). "In contrast, eight genes (COL1A1, COL5A1, COL1A2, COL3A1, WNT2, C1QTNF3, ADAMTS2, GXYLT2) exhibited elevated expression in tumor compared to normal tissue." (PMID 39062832, 2024). "A large number of clinical and basic experiments have shown that the members of Wnt family, including WNT1, WNT2, WNT3A etc., are highly expressed in malignant tumour tissues, which can enhance tumour occurrence, growth and metastasis." (PMID 36646807, 2023). "The Wnt1 and Wnt2 usually involved in Wnt/PCP signalling pathway, which plays key roles in guiding cell polarity and tumour cell invasiveness." (PMID 36766788, 2023). "Genes in the Wnt signaling pathway such as, WNT2 and WNT5A, were upregulated in tumor fibroblasts while SFRP1, an inhibitor of Wnt signaling was downregulated." (PMID 35999201, 2022). "Conversely, WNT5A, WNT7B, WNT2, WNT7A, WNT10A and WNT3 were tumor-positive WNTs, which significantly increased in many carcinomas." (PMID 35850748, 2022).
tumor (continued). "Androgen-signaling inhibition elevated Wnt2, Wnt3a, and Wnt5a expression in CAF, and enhanced tumor epithelial cell survival." (PMID 35884514, 2022). "WNT2 and WNT2B produced by the tumor microenvironment had high expression in the classical subtype tumors, but low expression in the squamous subtype." (PMID 35536676, 2022). "Except IL-6, CAFs-derived Wnt2 can also increase tumor angiogenesis in CRC, owing largely to Wnt2-upreglated expression of some proangiogenic proteins." (PMID 34660589, 2021). "A panel of tumor-derived extracellular vesicle markers, including EGFR, EPCAM, HER2, MUC, GPC1, WNT2, and GRP94, was investigated." (PMID 33803470, 2021). "Another protein of the Wnt pathway, increased expression of which in tumor cells is important for the initiation of inhibition of CRC angiogenesis process, is Wnt2." (PMID 33276489, 2020). "Subsequently, we verified the correlation between the expressions of Wnt2 and COL8A1 in 158 tumor tissues of COAD patients by immunohistochemical analysis (P = 0.017)." (PMID 32983993, 2020). "In the current study, we demonstrated for the first time that Wnt-2 signaling is activated through the Frizzled-8 receptor in NSCLC cells, and that a novel dnhWnt-2 construct reduces tumor growth in NSCLC cells and in a xenograft mouse model." (PMID 23815780, 2013). "A novel dnhWnt-2 construct significantly inhibits Wnt-2 signaling, reduces colony formation of NSCLC cells in vitro and tumor growth in a xenograft mouse model." (PMID 23815780, 2013). "Preclinical studies using human MPM cell lines have shown that WNT2 inhibition via siRNA or monoclonal antibodies induces tumor programmed cell death, even in β-catenin-independent pathways, suggesting a noncanonical role of WNT2 in cell survival." (PMID 40453074, 2025). "Abnormal expression of Wnt2 protein could be seen in CRC cells, and overexpression of Wnt2 protein increases the tumor volume and vascular density of CRC xenografts." (PMID 40308773, 2025). "Our findings suggest that WNT2 and WNT7B act as potential oncogenic drivers, whereas WNT11 may serve as a tumor suppressor." (PMID 41044153, 2025). "WNT2 and WNT11, which are positively correlated with immune scores in BRCA, are key players in TME modulation and may affect tumor progression and immune evasion." (PMID 41044153, 2025). "As multiple reports have indicated that Wnt-2 is expressed by CAFs, we anticipated that Wnt-2 may be interacting with TNC via CAFs adjacent to invasive, TNC-expressing tumor cells." (PMID 39951495, 2025). "Many in vitro and in vivo studies show that in different tumor types, such as colorectal, lung, breast, or hepatocellular cancer, specific WNTs, including WNT1, WNT2, WNT3A, WNT6, WNT8B, WNT7B, and WNT16B, can activate canonical Wnt signaling and support tumor proliferation." (PMID 36982422, 2023). "We also found enrichment for other tumor progression-related processes such as cell migration and Wnt signaling (examples of differentially expressed genes: SCUBE3, SEMA3C, WNT2)." (PMID 37085135, 2023). "Targeting PDGF receptor signaling, FGF1/FGFR3, FAK pathway, HGF secretion, endoglin, activin A, Wnt2 and fatty acid oxidation, matrix metalloprotease 9 (MMP9) and hedgehog (Hh) signaling could delay tumor growth." (PMID 36139552, 2022). "Knockdown of WNT2 expression suppressed cancer cell growth, reduced cellular invasion and migration, reduced β-catenin target-gene expression (MMP3/9) in vitro, and inhibited xenograft tumor growth in vivo." (PMID 32699215, 2020). "We recently identified WNT2 to be specifically upregulated in stromal fibroblasts of CRC, being an autocrine factor to promote CAF migration, ECM remodeling, and invasion, thereby, as a secondary effect, influencing tumor cell invasion and dissemination." (PMID 31667643, 2020).
tumor (continued). "Of note, the distribution of small, medium, and large vessels was not altered in the cancers indicating that WNT2 expression had a general effect on tumor angiogenesis and not on vessel maturation." (PMID 31667643, 2020). "However, the regulation of known angiogenic inducers by WNT2 prevails in CAFs of CRC patients, thus leading to a shift in the angiogenic balance towards a pro-angiogenic milieu in the tumor stroma." (PMID 31667643, 2020). "Moreover, squamous cell carcinoma antigen, an tumor marker for predicting PLNM, was sinificantly correlated with WNT2 expression level (P = 0.029)." (PMID 27513465, 2016). "Hence, in human fibroblasts, the Wnt2-HIRA-SAHF signaling axis and the pRB tumor suppressor pathway coordinately regulate formation of SAHF." (PMID 20569479, 2010). "Indeed, Wnt ligand signaling plays a key role in PDAC progression and therapeutic resistance, and tumor-proximal fibroblasts are seen to be strong contributors to the Wnt ligand pool with high level expression of the ligands WNT5A, WNT11, WNT2, WNT5, WNT5A, and WNT5B." (PMID 37350578, 2023). "In parallel, SOX2 was found to cooperate with important oncogenes, like Wnt1 (OMIM: 164820), Wnt2 (OMIM: 147870), c‐Myc (OMIM: 190080), and Notch1 (OMIM: 190198), to promote lung tumor occurrence, while downregulation of SOX2 inhibited proliferation and induced apoptosis in tumor cells." (PMID 32130794, 2020). "Consequently, molecular profiles, at least of Wnt2, were considered independent of the tumor location." (PMID 31468733, 2019). "We checked for changes in expression of Wnt ligands, and although there was a trend toward significantly increased expression of Wnt2, Wnt5b, Wnt8b, and Wnt10b specifically in the tumor and not the neighboring normal tissue, the changes did not quite reach statistical significance (Fig EV2A and B)." (PMID 28183841, 2017). "Regardless of the basis for these differences, it will ultimately be important to determine whether the relative ease of transformation of mouse cells, compared to human cells, stems, at least in part, from their failure to regulate this Wnt2-HIRA-SAHF axis, a candidate tumor suppressor pathway." (PMID 20569479, 2010). "CAF-derived WNT2 reduces CD11c+ and CD103+ DC differentiation, leading to diminished tumor antigen presentation and CD8+ T cell activation, while not affecting overall CD45+ immune cell infiltration." (PMID 40453074, 2025). "In ICC samples, the expression value of HBV-integrated genes, including MET, WNT2, BRD9, and TERT, in tumor seems to be higher than the paired non-tumor tissues." (PMID 36123506, 2022). "Of note, the correlation between the WNT2/LRP5/LRP6 signature and the mesenchymal signature was decreased when using STAD tumor data, compared to the non-canonical signatures." (PMID 33869179, 2021). "WNT2 can activate both canonical and non-canonical WNT signalling, while FZD5 and FZD9, both of which are expressed in the high-amplified tumours, activate different branches of the pathway (FZD5 the canonical pathway and FZD9 the non-canonical pathway)." (PMID 34003256, 2021).